ZEB1 (zinc finger E-box binding homeobox 1)
Diseases named in the same sentence as ZEB1 in open-access papers (continued):
Sharing a sentence is not in itself a finding about the gene and the disease.
leukemia (15 papers, 2015 to 2025). A malignant (clonal) hematologic disorder, involving hematopoietic stem cells and characterized by the presence of primitive or atypical myeloid or lymphoid cells in the bone marrow and the blood. "ZEB1 is frequently disrupted in adult T‐cell lymphoma/leukemia cells, which is associated with leukemogenesis." (PMID 39887881, 2025). "MEF2C (often deregulated and associated with recurrence in leukemia) and ZEB1 (shown to modulate hematopoietic stem cell fates) are also inactive in the blood (TF activity -0.882 and -1.532, respectively)." (PMID 38165902, 2024). "Strikingly, increased H3K4 trimethylation occurred in the promoters and ORFs of several of the same genes that are frequently upregulated in MLL1F leukemias including HoxA9-13, Meis1, and ZEB1." (PMID 39342993, 2024). "In agreement with such a scenario, EMT inducers such as Twist, Zeb1, Zeb2, and Snail/Slug have been shown to play critical roles in HSCs and in leukaemia." (PMID 30658474, 2019). "For example, the knockdown of ZEB1 in a leukemia model drastically reduced the blast invasion." (PMID 32059478, 2020). "The knockdown of Zeb1 in MLL/AF9-driven leukaemia drastically reduces leukaemic blast invasion." (PMID 30658474, 2019). "In this study, we found that the expression of ZEB1 was significantly higher in AML patients and several leukaemia cell lines compared with normal control by analysing the data in public databases and Western blot." (PMID 33960640, 2021). "Similar to solid tumors, in leukemia, EMT-TFs, such as TWIST, ZEB1-2, and SNAI1-2, play critical roles." (PMID 32059478, 2020). "A recent article showed that knockdown of ZEB1, an important EMT-related transcription factor, in MLL/AF9-driven leukaemia significantly reduced leukemic blast invasion." (PMID 27713544, 2016). "In addition, compared with normal human monocytes, multiple leukaemia cell lines, such as NB4, THP‐1 and K562, exhibited a significantly elevated protein level of ZEB1." (PMID 33960640, 2021). "Interestingly, there was no additional delay in the progression of leukemia observed when both Zeb1 and Zeb2 from the MLL-AF9 model were knocked out." (PMID 39941895, 2025). "The complex role of ZEB1 within AML extends to its effect on the immunological landscape, where it downregulates CD8 T cell activity and promotes the expansion of Th17 cells, enhancing the survival and proliferative capabilities of leukemia cells in the AML niche." (PMID 39200378, 2024). "Although SNAI1, ZEB1, and ZEB2 were not upregulated in RNA-seq data of Adh ALL patient samples, they have putative roles in leukemia development/progression, and we observed SNAIL (SNAI1) and ZEB1 but not ZEB2 to be highly expressed in Adh leukemic cell lines." (PMID 37453060, 2023).
Obesity (15 papers, 2009 to 2025). Accumulation of substantial excess body fat. "Both miR-200b and miR-200c have been found to downregulate ZEB1, contributing to the pro-inflammatory state associated with obesity." (PMID 34690698, 2021). "Mmu-miR-200b and mmu-miR-200c(members of the mmu-miR-200 family), mmu-miR-203 and mmu-miR-192 target Zeb1 and Zeb2 that regulate epithelial to mesenchymal transition and have recently been implicated in adipogenesis and obesity." (PMID 22496873, 2012). "Considering that obesity is defined as increased fat accumulation, we used body weight to investigate whether bone ZEB1 expression was linked to this pathology, identifying a significant correlation between the expression of this TF and body weight." (PMID 36890579, 2023). "Loss of Zeb1 in these cells result in an increase of islet mass, impaired glucose tolerance, and sensitizes to develop liver and pancreas steatosis during diabetes and obesity." (PMID 34112759, 2021). "The pathogenetic mechanism for one or both of these Zeb1 alleles may also underlie a locus for susceptibility to obesity on human chromosome 10p11, which includes the human ZEB1 gene." (PMID 21980308, 2011). "ZEB1 is a zinc-finger protein involved in adipocyte differentiation in mouse, as well as in obesity development in humans." (PMID 36890579, 2023). "In an epigenetic association study, researchers found that Etv5, Nudt3, Wwox, Zeb1, and Maf DNA methylation alterations were related to obesity in peripheral blood leukocytes of humans." (PMID 35458198, 2022). "In order to begin to delineate the potential mechanisms by which ZEB1 represses obesity, food intake and activity were measured." (PMID 20041147, 2009). "Given previous studies demonstrating the involvement of ZEB1 in obesity, the authors propose that Dio3os may contribute to obesity by trans-regulating ZEB1." (PMID 41235096, 2025). "Data obtained showed a positive correlation between both genes, however PPARG expression did not correlate with weight nor BMI, indicating a relevant role for ZEB1 in obesity-associated bone alterations." (PMID 36890579, 2023). "Zeb1 may regulate adipocyte differentiation in obesity and may also play a role in insulin resistance in adipose tissue and apoptosis in pancreatic beta cell during diabetes." (PMID 36550567, 2022). "Just as miR-200b and miR-200c downregulate ZEB1 in obesity, they may also play a role in its regulation during periods of ischemia." (PMID 34690698, 2021). "Interestingly, previous research linked sequence variation of the genomic locus in which Zeb1 is located to body fat distribution and obesity, supporting a possible role for ZEB1 in these processes." (PMID 25163748, 2014). "Based on genome wide association studies that link obesity to the region on chromosome 10 that encompasses the TCF8 gene and on the ability of ZEB1 to impact the differentiation of other mesenchymal cell lineages, we hypothesized that ZEB1 opposes obesity." (PMID 20041147, 2009). "Additionally, the role that the miR-200 family plays in inducing inflammation in obesity through regulation of ZEB1 may also serve as a mechanism for inducing inflammation in neurodegenerative disorders." (PMID 34690698, 2021). "Moreover, we have validated the algorithm on tissue-specific and osteoblastogenic DNA-methylation signatures, identifying ZEB TF ratios as modulators of differentiation of MSCs to osteoblasts and adipocytes, and ZEB1 as a critical TF in obesity-related bone adiposity." (PMID 36890579, 2023). "Interestingly, PPARG expression did not correlate with weight or BMI, which suggests that the obesity effects on bone adiposity might imply ZEB1 modulation rather than major adipogenesis inducer PPARG." (PMID 36890579, 2023).
oral squamous cell carcinoma (15 papers, 2014 to 2024). "Previous laser capture microdissection studies in both CRC and oral squamous cell carcinomas show that tumor buds over-express EMT-related genes such as ZEB1, ZEB2, DES, TGFB3, and VIM in comparison to the main tumor mass." (PMID 31316988, 2019). "RNA-sequencing analysis of tumor buds in oral squamous cell carcinomas showed that the protein level of ZEB1 was higher as compared to that in the tumor center, but lower than that in adjacent stromal cells." (PMID 27136592, 2016). "LncRNA CYTOR regulates mitochondrial metabolism and glycolysis of oral cancer cells via HNRNPC-mediated ZEB1 stabilization in oral squamous cell carcinoma, and the level of CYTOR could be upregulated by forkhead box D1 to promote EMT and chemoresistance in oral squamous cell carcinoma." (PMID 36814556, 2023).
posterior polymorphous corneal dystrophy (15 papers, 2009 to 2025). Posterior polymorphous corneal dystrophy (PPCD) is a rare mild subtype of posterior corneal dystrophy characterized by small aggregates of apparent vesicles bordered by a gray haze at the level of Descemet membrane, generally with no effect on vision. "Mutations in ZEB1 are known to be pathogenic causing posterior polymorphous corneal dystrophy-3, late-onset Fuchs endothelial corneal dystrophy, and keratoconus." (PMID 29110737, 2017). "In addition, we identified a pathogenic heterozygous variant in the ZEB1 gene that is a known cause of posterior polymorphous corneal dystrophy 3 (OMIM #609141) and Fuchs endothelial corneal dystrophy 6 (OMIM #613270)." (PMID 39495751, 2024). "Mutations in three genes are known to cause posterior polymorphic corneal dystrophy: OVOL2, ZEB1, and GRHL." (PMID 40002778, 2025). "Posterior polymorphous corneal dystrophy (PPCD), associated with ZEB1 insufficiency, provides a new biological context in which to understand and evaluate the classic EMT/MET paradigm." (PMID 31194824, 2019). "Similarly, mutations in the ZEB1 gene have been associated with late onset of FECD and posterior polymorphous corneal dystrophy." (PMID 40002778, 2025). "The symptoms observed in ZEB1 null mice were more representative of posterior polymorphous corneal dystrophy (PPCD), where the expression of epithelial genes was observed in the endothelium, suggesting that ZEB1 may play a role in the suppression of an epithelial phenotype." (PMID 40214459, 2025). "Mutations of ZEB1 have been linked to multiple corneal genetic defects, particularly to the corneal dystrophies including keratoconus (KD), Fuchs endothelial corneal dystrophy (FECD), and posterior polymorphous corneal dystrophy (PPCD)." (PMID 33923743, 2021). "Although haploinsufficiency of ZEB1 in humans and mice is sufficient to cause posterior polymorphous corneal dystrophy, no other significant phenotypes have been reported; so, it was not clear whether metabolic consequences could be detected in the heterozygotes." (PMID 20041147, 2009). "They show phenotypic overlap with posterior polymorphous corneal dystrophy (PPCD) caused by pathogenic variants in OVOL2, ZEB1, and GRHL2, but no genetic cause for PCVs has been identified, although an association with x-linked megalocornea was noted in one case." (PMID 36079096, 2022).
oral cancer (14 papers, 2016 to 2025). "The results showed that ZEB1 expression was positively associated with oral cancer cell migration and invasion levels." (PMID 35963855, 2022). "Elevated expression of Zeb1 in mouse oral cancer cells increases the endogenous levels of Zeb2, and conversely, heightened Zeb2 expression similarly upregulates Zeb1." (PMID 40703656, 2025). "In contrast, the protein expression of ZEB1 in oral cancer cells showed a marked reduction upon transfection with these miRNAs, which confirmed their inhibitory capacity." (PMID 36982993, 2023). "The results showed that deletion of either CYTOR or HNRNPC promoted the degradation of ZEB1 mRNAs in oral cancer cells." (PMID 35963855, 2022). "To investigate the role of ZEB1 in OSCC, we next generated HN6 and Cal27 stable ZEB1 KD and OE cell lines via lentiviral infection to evaluate its effects on oral cancer cell migration and invasion." (PMID 35963855, 2022). "The increased expression of ZEB-1 and decreased E-cadherin contribute to poor survival from oral cancer." (PMID 36146567, 2022). "Subsequent WB assays confirmed that CYTOR expression levels shared a positive relationship with ZEB1 protein accumulation, and si-CYTOR treatment attenuated ZEB1 protein expression in a dose-dependent manner in both oral cancer cells and 293 T cells." (PMID 35963855, 2022). "Here, we found that CDDP induced the conversion of CD44v to CD44s in oral cancer cells, resulting in ZEB1-mediated EMT induction." (PMID 29515788, 2018). "As CD44s induces GFP expression even in E-cad (+) cells, these results suggest that CD44s up-regulates ZEB1 in CDDP-resistant oral cancer cells by suppressing miR-200c." (PMID 29515788, 2018). "Resveratrol is a natural polyphenolic flavonoid with anti-fibrosis activity in various tissues and has the capability to inhibit ZEB1 in oral cancer cells." (PMID 26934322, 2016). "Therefore, understanding the regulatory mechanisms of the ZEB1 machinery is important in overcoming drug resistance in oral cancer." (PMID 35204785, 2022). "For example, CD44 promotes EMT by upregulating ZEB1 in oral cancer cells." (PMID 36429098, 2022). "OVOL1/2 transcriptional factors can impress ZEB-1 transcriptional factors associated with EMTvia a feedback loop and regulate the splicing of mRNA via epithelial splicing regulatory protein 1 (ESRP1) induction in oral cancer." (PMID 36146567, 2022). "Collectively, these data indicated that CYTOR could affect the ability of HNRNPC to interact with ZEB1, further enhancing ZEB1 mRNA stability in oral cancer cells." (PMID 35963855, 2022). "Here, we separately overexpressed ZEB1 and ZEB2 in C57BL/6 mouse oral cancer (MOC) cells and investigated their cellular characteristics, including E‐cadherin levels, motile properties, chemoresistance, and metastatic ability in immunocompetent mice." (PMID 39362647, 2024). "Thus, our study identified new interactions involving EMT, ZEB1, and miRNAs wherein miR-139-5p and miR-200c-3p negatively regulated ZEB1 mRNA levels in the pharyngeal cancer cell line (FaDu) while miR-199b-5p upregulated them in the oral cancer cell line (HN13)." (PMID 36982993, 2023). "In this study, we show that CYTOR regulates ZEB1 via HNRNPC-mediated mRNA stabilization to alter energy metabolism, ultimately facilitating metastasis of oral cancer cells." (PMID 35963855, 2022). "miR-200 family members directly bind to ZEB1 and ZEB2 mRNAs in many types of cancers, including oral cancer, and induce EMT by decreasing ZEB1 and ZEB2 expression." (PMID 35204785, 2022). "To confirm that ZEB1 could physically bind to the SIRT3 and COX10 promoter regions in oral cancer cells, we conducted ChIP and Dual-luciferase reporter assays." (PMID 35963855, 2022).
oral cancer (continued). "Evaluation of aerobic glycolysis and mitochondrial respiratory function in these ZEB1 KD and OE cell lines showed that ECAR and OCR rates were significantly higher under ZEB1 overexpression and significantly lower upon ZEB1 knockdown compared to control oral cancer cells." (PMID 35963855, 2022).
cholangiocarcinoma (13 papers, 2016 to 2025). A carcinoma that arises from the intrahepatic biliary tree (intrahepatic cholangiocarcinoma) or from the junction, or adjacent to the junction, of the right and left hepatic ducts (hilar cholangiocarcinoma). "PDT can up-regulate the expression of SLC2A1, SLC2A6, and SLC7A5 and inhibit the expression of ZEB1, and four ferroptosis-sensitive genes are associated with the prognosis of patients with cholangiocarcinoma." (PMID 37894410, 2023). "A study obtained four genes associated with ferroptosis (SLC2A1, SLC2A6, SLC7A5, ZEB1) by analyzing RNA-seq data after PDT in cholangiocarcinoma." (PMID 37894410, 2023). "Butyrate enhanced the anti-cancer effects of HDAC6 inhibitors in cholangiocarcinoma (CCA) by decreasing Zeb1 expression." (PMID 36076996, 2022). "In cholangiocarcinoma, overexpression of the transcription factor zinc finger E-box-binding homeobox 1 (ZEB1) in tumor cells leads to increased CTGF expression." (PMID 35159011, 2022). "In human cholangiocarcinoma, ZEB1 is expressed in CAFs, correlating with cellular communication network factor 2 (CCN2) gene (encoded for CTGF) expression." (PMID 35159011, 2022). "ZEB1, serving as a transcription factor promoting the EMT process, is associated with the stem-like properties of cholangiocarcinoma (CCA) cells, which can be explained by the fact that FBXW7 dampens EMT and stemness of CCA cells via the mTOR/ZEB1 signaling pathway." (PMID 35515121, 2022). "DHM can enhance miR-455 expression, which decreases the expression of ZEB1, p-PI3K, and p-Akt in cholangiocarcinoma cell lines RBE and TFK-1 and suppresses cell proliferation and EMT in cholangiocarcinoma." (PMID 35884547, 2022).
head and neck cancer (13 papers, 2014 to 2025). A primary or metastatic malignant neoplasm affecting the head and neck. "However, for some types of cancer, such as head and neck carcinoma, it has been shown that ZEB1 overexpression increased the tumor susceptibility to ferroptosis and anti-VEGF-A treatment can be considered as an option for use in combination with ferroptosis inducers." (PMID 41226394, 2025). "In head and neck cancer, manipulation of several EMT markers/drivers, including E‐cad, ZEB1, SIRT1, and the miR‐200 family, causes dramatic changes in ferroptosis sensitivity." (PMID 37496319, 2023). "Within head and neck cancer, ZEB1 overexpression was found in cells enriched for CD133 and was associated with increased tumor initiation, again suggesting the importance of ZEB1 and the EMT in the CSC phenotype." (PMID 35047489, 2021). "Other EMT-related transcriptional factors, like Twist and ZEB1, were also evaluated in control and head and neck cancer tissue biopsies." (PMID 33673269, 2021). "Contrarily, co-overexpressing Zeb1 and Zeb2 elevated the emigration capability of the head and neck cancer cells." (PMID 32280305, 2020). "Zeb1 and Zeb2 knock-down in the head and neck cancer cells diminished CSC features, including emigration, self-renovation capacities, and stemness markers expressions." (PMID 32280305, 2020). "Knockdown of Zeb1 and Zeb2 in head and neck cancer cells decreased their CSC properties such as self-renewal capacity, the expression of stemness markers, and drug resistance." (PMID 27259269, 2016). "Conversely, co-overexpression of Zeb1 and Zeb2 enhanced sphere-forming ability of head and neck cancer cells." (PMID 27259269, 2016). "Increasing evidence suggested that microRNA mediated E-cadherin expression in the head and neck cancers by directly/indirectly targeting the transcription suppressors of E-cadherin, ZEB1 and ZEB2." (PMID 25161999, 2014). "Likewise, the ALDH+ head and neck cancer cells also exhibited higher ZEB1 expression levels." (PMID 38139138, 2023).
diffuse large B-cell lymphoma (12 papers, 2018 to 2025). "In patients with diffuse large B-cell lymphoma, ZEB1 expression has been associated with adverse clinical presentation and poor outcome." (PMID 32046309, 2020). "By regulating the PD-1/PD-L1 checkpoint, there was a positive feedback loop between SNHG14/miR-5590–3p/ZEB1 that led to the progression of diffuse large B-cell lymphomas and immune evasion." (PMID 40561678, 2025). "For instance, the up-regulated lncRNA in diffuse large B cell lymphoma SNHG14 adsorbs miR-5590-3p to enhance expression levels of ZEB1, thus activating the PD-1/PD-L1 pathway and inducing immune evasion." (PMID 36405753, 2022). "More recently, ZEB1 has been shown to be upregulated in diffuse large B-cell lymphoma tissues and cell lines and involved in a positive feedback loop that promotes diffuse large B-cell lymphoma progression and immune evasion." (PMID 32046309, 2020). "The ribonucleic acid expression of ZEB1, and therefore the macromolecule expressions of ZEB1 and PD-L1, in diffuse large B-cell lymphoma (DLBCL) cells was reduced under SNHG14 silencing." (PMID 35464451, 2022). "For example, in diffuse large B-cell lymphoma, the lncRNA SNHG14 upregulates the mRNA ZEB1 by competitively binding to miR-5590-3p, and ZEB1 positively activates SNHG14 and PD-L1, thereby promoting immune escape of tumor cells." (PMID 38485995, 2024). "In diffuse large B cell lymphoma (DLBCL) cells, miR-8890-3p is capable of suppressing ZEB1, while lncRNA SNHG14 conversely reduces the expression of miR-8890-3p to activate ZEB1." (PMID 32664703, 2020). "For example, the interaction between lncRNA SNHG14 and miR-5590-3p upregulates Zinc finger E-box-binding homeobox 1 (ZEB1) to activate the PD-1/PD-L1 immune checkpoint, leading to the inactivation of CD8 + T cells and promoting immune escape of tumor cells in diffuse large B-cell lymphoma." (PMID 37968670, 2023).